LEP (leptin)
Description:
Key player in the regulation of energy balance and body weight control. Once released into the circulation, has central and peripheral effects by binding LEPR, found in many tissues, which results in the activation of several major signaling pathways. In the hypothalamus, acts as an appetite-regulating factor that induces a decrease in food intake and an increase in energy consumption by inducing anorexinogenic factors and suppressing orexigenic neuropeptides, also regulates bone mass and secretion of hypothalamo-pituitary-adrenal hormones. In the periphery, increases basal metabolism, influences reproductive function, regulates pancreatic beta-cell function and insulin secretion, is pro-angiogenic for endothelial cell and affects innate and adaptive immunity (By similarity). In the arcuate nucleus of the hypothalamus, activates by depolarization POMC neurons inducing FOS and SOCS3 expression to release anorexigenic peptides and inhibits by hyperpolarization NPY neurons inducing SOCS3 with a consequent reduction on release of orexigenic peptides (By similarity). In addition to its known satiety inducing effect, has a modulatory role in nutrient absorption. In the intestine, reduces glucose absorption by enterocytes by activating PKC and leading to a sequential activation of p38, PI3K and ERK signaling pathways which exerts an inhibitory effect on glucose absorption. Acts as a growth factor on certain tissues, through the activation of different signaling pathways increases expression of genes involved in cell cycle regulation such as CCND1, via JAK2-STAT3 pathway, or VEGFA, via MAPK1/3 and PI3K-AKT1 pathways (By similarity). May also play an apoptotic role via JAK2-STAT3 pathway and up-regulation of BIRC5 expression. Pro-angiogenic, has mitogenic activity on vascular endothelial cells and plays a role in matrix remodeling by regulating the expression of matrix metalloproteinases (MMPs) and tissue inhibitors of metalloproteinases (TIMPs). In innate immunity, modulates the activity and function of neutrophils by increasing chemotaxis and the secretion of oxygen radicals. Increases phagocytosis by macrophages and enhances secretion of pro-inflammatory mediators. Increases cytotoxic ability of NK cells. Plays a pro-inflammatory role, in synergy with IL1B, by inducing NOS2 which promotes the production of IL6, IL8 and Prostaglandin E2, through a signaling pathway that involves JAK2, PI3K, MAP2K1/MEK1 and MAPK14/p38. In adaptive immunity, promotes the switch of memory T-cells towards T helper-1 cell immune responses (By similarity). Increases CD4(+)CD25(-) T-cell proliferation and reduces autophagy during TCR (T-cell receptor) stimulation, through MTOR signaling pathway activation and BCL2 up-regulation.
Synonyms: OB; OBS; LEPD
Tractability: Antibody: UniProt places it where antibodies can reach, with high confidence; its Gene Ontology location is reachable by antibodies, with high confidence; UniProt predicts a signal peptide or a membrane-spanning region; the Human Protein Atlas places it where antibodies can reach.
Safety:
Unwanted effects reported when the protein is acted on. In parentheses: how it was acted on, where the effect was seen, and who reports it.
extreme weight gain (source: ClinPGx)
weight gain (source: ClinPGx)
Gene: Protein-coding gene on chromosome 7 (128,241,278 to 128,257,629, forward strand). Ensembl gene ENSG00000174697.
Subcellular location: Secreted
Subcellular location (Human Protein Atlas): Plasma membrane; Vesicles; Predicted to be secreted
Pathways (Reactome):
Metabolism of proteins: Synthesis, secretion, and deacylation of Ghrelin; Synthesis, secretion, and inactivation of Glucagon-like Peptide-1 (GLP-1)
Developmental Biology: Transcriptional regulation of white adipocyte differentiation
Signal Transduction: Signaling by Leptin
Gene Ontology:
Molecular function: hormone activity; leptin receptor binding; protein binding; DNA binding; peptide hormone receptor binding; signaling receptor binding
Biological process: activation of protein kinase C activity; angiogenesis; cell surface receptor signaling pathway via STAT; cellular response to leptin stimulus; intestinal absorption; leptin-mediated signaling pathway; negative regulation of autophagy; negative regulation of D-glucose import; placenta development; positive regulation of developmental growth; positive regulation of interleukin-6 production; positive regulation of interleukin-8 production; positive regulation of MAPK cascade; positive regulation of p38MAPK cascade; positive regulation of receptor signaling pathway via JAK-STAT; positive regulation of T cell proliferation; positive regulation of TOR signaling; prostaglandin secretion; regulation of angiogenesis; regulation of cell cycle; regulation of cytokine production involved in inflammatory response; regulation of endothelial cell proliferation; regulation of natural killer cell activation; regulation of natural killer cell mediated cytotoxicity; regulation of natural killer cell proliferation; and 60 more
Cellular component: receptor complex; cytosol; extracellular region; cytoplasm
Genetic constraint (gnomAD): Loss-of-function variants: 9 observed, 13.79 expected, observed/expected ratio (o/e) 0.65, 90% interval 0.39 to 1.14. The synonymous counts are far from expectation, so gnomAD's model fits this gene poorly and the ratio says little. Missense variants: 134 observed, 205.88 expected, observed/expected ratio (o/e) 0.65, 90% interval 0.56 to 0.75. Synonymous variants: 112 observed, 84.67 expected, observed/expected ratio (o/e) 1.32, 90% interval 1.13 to 1.55.
Homologues: Orthologues: chimpanzee LEP (99% identical), macaque LEP (90% identical), pig LEP (85% identical), mouse Lep (83% identical), rat Lep (82% identical), dog LEP (80% identical), rabbit LEP (80% identical), guinea pig LEP (56% identical), tropical clawed frog lep (36% identical).
Diseases named in the same sentence as LEP in open-access papers:
LEP is named in the same sentence as 966 diseases in open-access papers, as found by Europe PMC text mining. Sharing a sentence is not in itself a finding about the gene and the disease. The quoted sentences say what the papers report.
Obesity (7,875 papers, 2001 to 2026). Accumulation of substantial excess body fat. "Dysfunction of the EPAC-leptin axis is one of the crucial pathological mechanisms underlying obesity and related metabolic diseases." (PMID 41503874, 2026). "ex Baker, has been reported to exhibit anti-obesity and muscle-protective potential; however, its effects on obesity-related muscle dysfunction and the underlying mechanisms in a leptin-deficient model remain to be fully elucidated." (PMID 42252898, 2026). "In RRMS, obesity is associated with elevated serum and CSF levels of pro-inflammatory cytokines such as IL-6 and adipokines, including leptin, resistin, and chemerin, alongside reduced levels of the anti-inflammatory adipokine adiponectin." (PMID 41562846, 2026). "Leptin-deficient ob/ob mice, which develop profound hyperphagia and severe obesity, serve as robust models for elucidating the pathological mechanisms underlying obesity-induced salivary gland dysfunction." (PMID 41516387, 2026). "Dysregulation of leptin signalling has been closely linked to obesity, systemic inflammation, and the pathogenesis of T2DM." (PMID 41549047, 2026). "This study established ferroptosis as a critical driver of salivary gland dysfunction in a leptin-deficient mouse model of obesity." (PMID 41516387, 2026). "MCF-7 and MDA-MB-231 BC cells were exposed to leptin at 10 ng/mL (lean-associated levels) and 100 ng/mL (elevated levels linked to obesity)." (PMID 41562922, 2026). "It has been shown that obese individuals with insulin resistance have abnormal levels of adipokines in the serum—reduced levels of adiponectin and elevated levels of leptin—which are also associated with an increased risk of obesity-related cancer development." (PMID 41594284, 2026). "While it is also well-known that steroids can increase insulin resistance and enhance lipid accumulation, the hypothalamic damage caused by cranial radiotherapy is proposed to lead to leptin insensitivity and predispose individuals to obesity." (PMID 41530579, 2026). "Elevated serum leptin levels are frequently observed in breast cancer patients, a phenomenon closely linked to obesity-since adipose tissue is the primary source of leptin, excess adiposity (especially visceral obesity) drives chronic hyperleptinaemia." (PMID 41498391, 2026). "Previous research indicates that elevated leptin levels are linked with early puberty in girls with obesity, but this is less pronounced for boys." (PMID 41240372, 2026). "Mutations associated with monogenic obesity follow autosomal recessive (LEP, LEPR, POMC, and PCSK1) or autosomal dominant (MC4R, SH2B1, SIM1, GNAS) modes of inheritance." (PMID 41751424, 2026). "Monogenic non-syndromic obesity accounts for 2-3% of obesity in both children and adults and is most often attributable to mutations in genes encoding components of the leptin-melanocortin pathway." (PMID 41751424, 2026). "In this study, we used leptin-deficient (ob/ob) mice to elucidate the role of ferroptosis in obesity-associated salivary gland pathology." (PMID 41516387, 2026). "For instance, administration of leptin, a peptide hormone secreted by adipocytes and upregulated in obesity, in mice genetically deficient in leptin (ob/ob mice) acts on the liver to stimulate hepcidin production." (PMID 41275403, 2026). "To date, approximately 22 genes associated with obesity risk have been identified, including genes involved in the synthesis of proteins such as leptin, melanocortin, and pro-inflammatory cytokines." (PMID 41465437, 2025). "Research indicates a significant association between lower serum leptin levels and a reduced threshold for detecting sweetness during weight loss in both healthy individuals and females with obesity." (PMID 40309850, 2025). "The SNP analysis of the MC4R gene indicated that the rs17782313 polymorphism is correlated with obesity, particularly in conjunction with the LEP GG genotype." (PMID 41423640, 2025).
Obesity (continued). "The presence of this mutation, undetectable leptin, and severe obesity confirmed a diagnosis of monogenic leptin deficiency." (PMID 40415699, 2025). "Obesity is usually associated with excessive leptin release, and chronic obesity can be caused by high levels of leptin that continue to stimulate leptin receptors (LRs), resulting in resistance to leptin." (PMID 40406485, 2025). "Higher carotid artery intimal thickness and slower fluctuations in pulse width were linked to elevated leptin levels, especially in female participants with diabetes or obesity." (PMID 39620366, 2025). "The leptin-melanocortin pathway is the primary cause of monogenic obesity, and numerous genes, including AgRP, PYY (orexogenic) or MC4R, interfere with the appetite and weight regulation system." (PMID 40278960, 2025). "After biliopancreatic diversion (BPD), women with obesity exhibit a marked improvement in insulin sensitivity, which appears to be closely associated with changes in leptin signaling." (PMID 40500780, 2025). "Leptin has been implicated in the link between obesity and breast cancer and is associated with tumor progression, invasion, and treatment resistance in breast cancer." (PMID 41463012, 2025). "The ob/ob mouse model is characterised by a deficiency in leptin, leading to the spontaneous development of obesity and type 2 diabetes mellitus secondary to hyperglycemia and hyperinsulinemia." (PMID 40159625, 2025). "Long-term low-grade inflammation associated with increased weight and obesity can lead to reduced leptin sensitivity, impairing appetite regulation." (PMID 40077044, 2025). "A leptin gene mutation leads to obesity, hyperglycemia, and insulin resistance, making it one of the best models for DN research." (PMID 40732224, 2025). "It binds to hypothalamus receptors to decrease food intake; however, in subjects with obesity, persistent hyperleptinemia causes leptin resistance." (PMID 39837875, 2025). "The overproduction of these hormones, such as leptin, leads to proinflammatory environments with excess and sustained levels of obesity-associated hormones." (PMID 40722609, 2025). "Leptin replacement therapy is currently considered as the only effective treatment for monogenic leptin deficient forms of human obesity." (PMID 40415699, 2025). "They confirmed that TET2 deficiency ameliorates HFD-induced obesity and insulin resistance by partially decreasing leptin levels as well as that the expression of the leptin gene in adipocytes is regulated by TET2." (PMID 40620794, 2025). "Overconsumption of a palatable Western diet, a condition linked to central leptin resistance, contributes extensively to the current obesity epidemic." (PMID 40540394, 2025). "Even though, excess leptin hormones are produced in adipose tissue, obesity impaired its action on the HPG axis and cause reduced LH secretion and testosterone release." (PMID 40811476, 2025). "Hyperleptinemia, a hallmark of obesity, induces leptin resistance via diminished hypothalamic sensitivity, perpetuating metabolic disturbances such as IR and cardiovascular disease." (PMID 40692591, 2025). "The elevated leptin levels in our study confirm the presence of hyperleptinemia, a condition typically associated with obesity, which increases the risk of cardiovascular diseases." (PMID 41334630, 2025). "A Swedish study in the general population showed significantly higher plasma leptin levels among patients with acute myocardial infarction, emphasizing the role of leptin as a key factor in obesity-associated CV risk." (PMID 40283183, 2025). "Differently, monogenic obesity results from a mutation in a single gene of the leptin–melanocortin pathway and presents with early-onset severe obesity associated with hyperphagia and additional clinical features." (PMID 40428410, 2025). "In a US cohort increasing leptin trajectories during childhood were linked to higher risk of obesity." (PMID 39899498, 2025).
Obesity (continued). "The ability of exogenous leptin to correct the obesity and other defects associated with leptin deficiency initially suggested the potential utility of leptin as a therapy for obesity." (PMID 40393800, 2025). "We found that a complete absence of maternal Sst expression increased the risk of male offspring to diet-induced obesity and severe insulin and leptin resistance." (PMID 40066865, 2025). "Leptin metabolism disturbances are one of the factors resulting in developing obesity, including leptin resistance, leptin deficiency or secretion of damaged molecules." (PMID 40426925, 2025). "Adding to the hormonal complexities, obesity is associated with leptin resistance, where elevated leptin levels fail to suppress appetite due to impaired hypothalamic signaling." (PMID 40959347, 2025). "Decreased adiponectin and increased leptin are associated not only with weight gain and obesity, but also with increased chronic inflammation in dogs and cats." (PMID 40552080, 2025). "A birth cohort in the United States (US) observed distinct leptin trajectories in children that were linked to higher risk of obesity in adolescence." (PMID 39899498, 2025). "A loss-of-function leptin mutation was among the first discovered monogenic causes of human obesity." (PMID 40427545, 2025). "Hyperleptinemia and leptin resistance are common in obesity-associated aging states, and regular exercise, particularly when accompanied by weight loss, can reduce circulating leptin levels." (PMID 41514897, 2025). "The highest prevalence of monogenic obesity was observed in a Pakistani population, where 30% of children with obesity carried pathogenic variants in the LEP, LEPR, and MC4R genes." (PMID 40149731, 2025). "Rather than acting independently, environmental exposures, including diet quality, physical activity, socioeconomic conditions, and psychosocial stress, interact with genetic predispositions (e.g., FTO, MC4R, LEP) to modulate obesity risk." (PMID 41302083, 2025). "Obesity is strongly associated with leptin resistance, where leptin is unable to suppress hunger, increase energy expenditure, and control glucose and lipid metabolism." (PMID 39857767, 2025). "Leptin, an adipokine associated with obesity, was highest in the mice fed an HFD for 16 weeks and lowest in the PEMF-FMT group." (PMID 40564914, 2025). "In general, obesity and insulin resistance are associated with increased proinflammatory cytokines from the adipose, including leptin, IL-6, TNFα, and resistin." (PMID 40985048, 2025). "Primary cilia, antenna-like sensory organelles protruding from the surface of most vertebrate cell types including neurons, have been implicated in hyperphagia-induced obesity and leptin resistance." (PMID 41251447, 2025). "The increase in adipose tissue associated with obesity is accompanied by elevated leptin concentrations." (PMID 41439942, 2025). "Second, Among obesity-related protein biomarkers, lower adiponectin levels and higher leptin and IGF-1 levels were associated with an increased BC risk." (PMID 40386557, 2025). "At the same time, while prior studies have focused on common obesity-associated SNPs or large CNVs, this study specifically investigated smaller CNVs in the genes involved in leptin signalling and insulin resistance." (PMID 40429924, 2025). "Obesity acts as a confounding factor, not only serving as a potential risk factor for neuroinflammatory diseases such as MS and AD but also inducing leptin resistance through which metabolic dysfunction drives immune dysregulation and neuroinflammation." (PMID 41516046, 2025). "Adiponectin counteracts leptin protumor effects, suggesting that obesity-associated breast carcinogenesis is mainly regulated by a leptin–adiponectin axis imbalance." (PMID 41463076, 2025). "BBSome deficiency reduces LepRb surface expression, which impairs leptin’s effects and probably contributes to obesity in BBS individuals." (PMID 41251447, 2025).